MIR523 (microRNA 523)
Synonyms: hsa-mir-523; MIRN523; mir-523
Gene: MicroRNA gene on chromosome 19 (53,698,385 to 53,698,471, forward strand). Ensembl gene ENSG00000283455.
Gene Ontology:
Biological process: miRNA-mediated post-transcriptional gene silencing
Homologues: Orthologues: chimpanzee ptr-mir-523 (98% identical), macaque mml-mir-523a (92% identical). Paralogues in human: MIR518E (91% identical), MIR518F (91% identical), MIR522 (90% identical), MIR518C (89% identical), MIR518D (89% identical), MIR520C (89% identical), MIR516A1 (87% identical), MIR519C (87% identical), MIR520F (87% identical), MIR521-1 (87% identical), MIR516A2 (86% identical), MIR516B1 (86% identical), and 12 more.